BTK (Bruton tyrosine kinase)
Diseases named in the same sentence as BTK in open-access papers (continued):
Sharing a sentence is not in itself a finding about the gene and the disease.
agammaglobulinemia (continued). "Because XLA is a monogenic disorder, correction of the singular BTK gene should result in disease correction of agammaglobulinemia, opening a promising avenue for a hematopoietic stem cell gene therapy approach to either add or restore BTK protein expression." (PMID 40917692, 2025). "Hypomorphic mutations in other IEI genes (BTK, GATA2, IL2RG, JAK3, RAG1, RAG2, etc.)have been previously found in patients with antibody deficiency and milder phenotypes or in CVID patients." (PMID 34975878, 2021). "Two patients, Patient 10 and 13, who were clinically diagnosed as agammaglobulinemia, had normal levels of BTK protein by immuno-SRM." (PMID 30564228, 2018). "The gene encoding the BTK molecule was isolated in 1993 and was named independently at the time as B cell progenitor kinase and agammaglobulinemia tyrosine kinase." (PMID 27590878, 2016). "It is caused by mutations of the Bruton tyrosine kinase (BTK) gene and is the most common form of inherited antibody deficiency." (PMID 24885015, 2014). "X‐linked agammaglobulinemia (XLA) is a congenital immunodeficiency disorder that results from impaired B‐cell differentiation due to Bruton tyrosine kinase (BTK) mutations, leading to a decrease in mature B‐cells, impaired antibody production, and hypogammaglobulinemia." (PMID 40276328, 2025). "A prime example is the absence of peripheral blood B cells in patients with agammaglobulinemia due to mutations in BTK or related genes in the BCR signaling pathway." (PMID 31552044, 2019). "Germline mutations in the gene encoding for BTK result in an almost complete absence of mature B cells and hypogammaglobulinemia, the hallmark of X-linked (Bruton’s) agammaglobulinemia." (PMID 30700842, 2019). "Mutations in BTK gene lead to an impaired B cell development resulting in absent or very low number of B-cells and profound hypogammaglobulinemia in patients affected by XLA." (PMID 28422989, 2017). "Not all patients with the early onset of infections, profound hypogammaglobulinemia, and markedly reduced or absent B cells are found to have BTK mutations." (PMID 27512878, 2016). "BTK, Bruton tyrosine kinase, is associated with agammaglobulinemia, an X-linked immunodeficiency that involves a failure in normal development of B lymphocytes, via missense mutations." (PMID 19765316, 2009). "Thus, BTK deficiency causes XLA and accounts for ∼85% of agammaglobulinemia cases." (PMID 37273190, 2023). "The defect in XLA resides in Bruton tyrosine kinase (BTK), also known as B cell progenitor kinase (BPK) or agammaglobulinemia tyrosine kinase (ATK), a key regulator in B-cell development." (PMID 34447768, 2021). "Mutations within the BCR signalosome such as BTK or BLNK usually result in absent protein expression, a severe block of BCR signaling and an arrest at the pre-B cell stage, subsequently leading to agammaglobulinemia." (PMID 30619340, 2018). "Defective BTK activity results in a block in the maturation of B cells in the bone marrow of XLA patients, leading to severely reduced or absent peripheral B cells and severe hypogammaglobulinemia." (PMID 40917692, 2025).
atrial fibrillation (47 papers, 2017 to 2025). A disorder characterized by an electrocardiographic finding of a supraventricular arrhythmia characterized by the replacement of consistent P waves by rapid oscillations or fibrillatory waves that vary in size, shape and timing and are accompanied by an irregular ventricular response. "Although these off-target effects contribute to the antitumor efficacy of BTK inhibitors, they are also associated with a range of adverse events, including hypertension, atrial fibrillation, bleeding complications, and impaired macrophage phagocytosis." (PMID 40453665, 2025). "Managing atrial fibrillation is particularly challenging, as the concurrent use of anticoagulants with BTK inhibitors increases the risk of bleeding." (PMID 40453665, 2025). "The toxicities associated with ibrutinib, a BTK inhibitor, include atrial fibrillation in up to 38% of patients, ventricular arrhythmias, HF, and hypertension." (PMID 38541800, 2024). "Other AEs associated with BTK inhibitor therapy such as atrial fibrillation, hypertension, major hemorrhage, cytopenia, and infection require immediate intervention and have the potential for life-threatening consequences." (PMID 37185435, 2023). "Several studies have identified potential risk factors for the development of atrial fibrillation during BTK inhibitor therapy including existing cardiac comorbidities, left atrial volume, older age, and being male." (PMID 37185435, 2023). "Ibrutinib, a BTK inhibitor, is associated with a 4-fold increase in atrial fibrillation and other arrhythmias." (PMID 32932930, 2020). "BTK inhibitors are associated with atrial fibrillation, hypertension, and bleeding due to abnormal platelet aggregation." (PMID 32932930, 2020). "Only ibrutinib (Bruton tyrosine kinase inhibitor) has been linked to instances of atrial fibrillation, ventricular arrhythmias, and sudden cardiac death." (PMID 31790629, 2019). "The proposed mechanism of atrial fibrillation caused by ibrutinib is related to the inhibition of Bruton's tyrosine kinase (BTK) and related kinases." (PMID 30062075, 2018). "In addition to atrial fibrillation, stroke is a major adverse event associated with next-generation BTK inhibitors, including acalabrutinib or zanubrutinib." (PMID 38541800, 2024). "Acalabrutinib’s enhanced specificity for BTK and/or less inhibition of C-terminal Src kinase may cause lower off-target effects, explaining the lower incidence of atrial fibrillation in our cohort of patients." (PMID 38824606, 2024). "Although BTK inhibitors may cause undesirable adverse events such as major hemorrhage, atrial fibrillation, and thrombocytopenia/neutropenia, these side effects often occur with irreversible BTK inhibitors." (PMID 38125430, 2023). "However, the first-in-class BTKi ibrutinib has some limitations, such as the development of resistance, mainly due to C481 BTK mutations, and its toxicity, including atrial fibrillation and bleeding, mainly related to off-target activity." (PMID 35159041, 2022). "The novel BTK inhibitor zanubrutinib has been associated with lower rates of atrial fibrillation than ibrutinib in a randomized study and could be considered in patients at a high risk of atrial fibrillation." (PMID 34531537, 2022). "Ibrutinib and acalabrutinib are both associated with an increased risk of atrial fibrillation (AF); however, the comparative risk of AF between these 2 BTK inhibitors remains largely unknown." (PMID 40038806, 2025). "Although atrial fibrillation is the most common MACE reported with BTK inhibitor treatment, ventricular arrhythmias, tachycardia, and sudden deaths have been reported with ibrutinib, acalabrutinib, and zanubrutinib, although their incidence is rare." (PMID 37185435, 2023). "Atrial fibrillation is among the most common AEs leading to treatment discontinuation on BTK inhibitor therapy." (PMID 37185435, 2023).
atrial fibrillation (continued). "Atrial fibrillation has consistently been reported more frequently in the BTK inhibitor arms than control arms in clinical trials." (PMID 37185435, 2023). "The rate of new atrial fibrillation events generally remains stable over the course of BTK inhibitor therapy." (PMID 37185435, 2023). "According to the literature on the first-generation BTK inhibitors, in our analysis the most reported CV events were atrial fibrillation, haemorrhage, and hypertension (44.1%)." (PMID 37654615, 2023). "The management of atrial fibrillation can be challenging in patients receiving BTK inhibitors as the treatment of atrial fibrillation often includes anticoagulants, which can exacerbate the bleeding risk already associated with BTK inhibitors." (PMID 37185435, 2023). "In particular, a grow incidence of atrial fibrillation, ventricular arrhythmias and sudden death with BTK inhibitors was identified in the literature." (PMID 37654615, 2023). "In direct comparison trials, atrial fibrillation was reported less frequently with second generation BTK inhibitors than with ibrutinib." (PMID 37185435, 2023). "Patients with atrial fibrillation have significantly lower cardiac PI3K-AKT activity, and the use of BTK attenuates the Akt response and thus predisposes to cardiac fibrosis and atrial arrhythmias, such as atrial fibrillation." (PMID 35642110, 2023). "Although ibrutinib, the first-generation BTK inhibitor, has been pioneering in the treatment of B-cell lymphoma, its adverse reactions are also worthy of attention, such as atrial fibrillation bleeding, diarrhea, rash, atrial fibrillation, and neutropenia." (PMID 36147349, 2022). "Atrial fibrillation is one of the most reported adverse events for ibrutinib and generally one of the top three concerns pushing for more selectivity in BTK inhibitors." (PMID 34803999, 2021). "Improving the selectivity of BTK inhibitors has been primarily aimed at improving their safety profiles where hemorrhage, atrial fibrillation, and hypertension are common adverse events." (PMID 34803999, 2021). "In patients, ibrutinib (inhibitor of Bruton tyrosine kinase, an upstream effector of PI3Kα) increased cardiac disorders (2-fold) and atrial fibrillation (3-fold), as well as instances of sudden death and ventricular arrhythmias." (PMID 31790629, 2019). "Recent clinical trials have demonstrated particularly high rates of atrial fibrillation with the targeted therapy ibrutinib, a covalent, irreversible inhibitor of Bruton’s tyrosine kinase (BTK)." (PMID 32153998, 2017). "This phenomenon is well established clinically: for example, the most frequent adverse event associated with ibrutinib, atrial fibrillation, is attributed to off-target inhibition of cardiac kinases rather than to BTK blockade itself." (PMID 41440767, 2025). "Patients receiving BTKis often require concomitant antithrombotic therapy for atrial fibrillation (AF), ischemic heart disease, or venous thromboembolism—conditions that may themselves be precipitated or exacerbated by BTK inhibition." (PMID 41376625, 2025). "It is unclear whether BTK inhibitor therapy should be paused until the resolution of atrial fibrillation." (PMID 37185435, 2023). "Another consideration would be to evaluate the combination of pevonedistat with “second-generation” BTK inhibitors (e.g., acalabrutinib, zanubrutinib) which may further mitigate the risks of bleeding and atrial fibrillation." (PMID 36631449, 2023). "Toxicities, such as atrial fibrillation, bleeding, or arterial hypertension, albeit limited, caused by inhibition of other non-BTK targets, such as ITK and EGFR underscores the need for more selective BTK inhibitors with fewer off-target effects." (PMID 34750354, 2021). "The combined inhibition of BTK (“on-target” effect) and other kinases (“off-target” effect) can have additive or synergistic anti-tumor effects but also induce undesired side effects, such as atrial fibrillation (AF) and bleeding." (PMID 34276674, 2021).
atrial fibrillation (continued). "Atrial fibrillation, rash and diarrhoea in patients treated with BTK inhibitors." (PMID 33777941, 2021). "BTK is expressed in human cardiac tissue and appears to be expressed greater in patients with atrial fibrillation compared to those in normal sinus rhythm, which could explain the pro-arrhythmogenic effects of ibrutinib in atrial dysrhythmias." (PMID 34798905, 2021). "Ibrutinib, a first‐generation Bruton tyrosine kinase (BTK) inhibitor, has significantly improved CLL treatment but is associated with adverse cardiovascular events such as atrial fibrillation (AF) and hypertension (HTN)." (PMID 40341807, 2025). "Atrial fibrillation was reported only with ibrutinib (5.8%); no cases were identified with the other BTK inhibitors." (PMID 39271521, 2025). "Unlike first-generation BTK inhibitors, the incidence of atrial fibrillation is negligible in patients treated with the new-generation BTK inhibitors." (PMID 37845755, 2023). "Treatment with BTK inhibitors, namely ibrutinib, reported significantly higher rates of arterial hypertension, atrial fibrillation, major bleedings, and arthralgia than non-BTK-based therapies." (PMID 35407474, 2022). "Meanwhile, no unique AEs related to BTK inhibitors (e.g., bleeding events, atrial fibrillation, and aspergillosis) were observed." (PMID 35004280, 2021). "Atrial fibrillation occurs in approximately 10% of patients over 36 months, and may be mediated by decreased PI3K-AKT signalling in cardiomyocytes due to BTK and Tec protein kinase inhibition." (PMID 35582452, 2020). "Although the mechanism of BTK inhibitors related to atrial fibrillation is still unclear, it is thought that the inhibition of PI3K signaling, which is crucial for cardiac protection under stress that is regulated by BTK and TEC, may play a role in the incidence of atrial fibrillation." (PMID 37845755, 2023). "Of note, atrial fibrillation is not seen in patients treated with other BTK inhibitors." (PMID 34897650, 2022). "Although one report suggests that ibrutinib-induced atrial fibrillation may be related to on-target toxicity via inhibition of BTK, newer BTK inhibitors such as acalabrutinib have not been associated with increased rates of AF, suggesting an off-target mechanism." (PMID 32153998, 2017).
rheumatoid arthritis (42 papers, 2015 to 2024). A chronic, systemic autoimmune disorder characterized by inflammation in the synovial membranes and articular surfaces. "The first-generation BTK inhibitor ibrutinib was initially synthesized in 2007 and described as an irreversible BTK inhibitor with potential therapeutic value in rheumatoid arthritis." (PMID 37696810, 2023). "Currently, through research on these activation mechanisms, kinases, such as JAK, MAPK, SYK, PI3K, NF-κB, and BTK, are being recognized as major targets for the development of rheumatoid arthritis treatments." (PMID 37623223, 2023). "Our data are also complementary to findings that demonstrate BTK inhibitors have promise in preclinical work in models of rheumatoid arthritis." (PMID 34897650, 2022). "Our data strengthen the case for using BTK inhibitors to reduce monocyte infiltration and macrophage activation in acute inflammatory diseases like sepsis, rheumatoid arthritis or cardiovascular disease including myocardial infarction or stroke." (PMID 34897650, 2022). "Initially designed as a treatment in the rheumatoid arthritis mouse model, ibrutinib, an orally bioavailable selective BTK inhibitor, has been approved for the treatment for the various B-cell malignancies and chronic graft-versus-host disease." (PMID 36521376, 2022). "Previous studies have showed that BTK can be detected in patients with lupus nephritis and rheumatoid arthritis." (PMID 33389462, 2021). "Several articles have reported increased BTK expression in B cells of lupus nephritis, rheumatoid arthritis, and other diseases." (PMID 33389462, 2021). "In the search of new BTK reversible inhibitors with enhanced selectivity for the treatment of rheumatoid arthritis (RA), RN486 was developed and examined in in vitro binding and competition studies, as well as in cell-based assays." (PMID 34349760, 2021). "Fenebrutinib (GDC-0853), a Bruton’s tyrosine kinase (BTK) inhibitor was investigated in a Phase 2 clinical trial in patients with rheumatoid arthritis (RA)." (PMID 31907670, 2020). "Herein, we report the design and synthesis of novel irreversible pyranochromenone-based BTK inhibitors with in vivo efficacy in a murine model of rheumatoid arthritis." (PMID 33113810, 2020). "In addition, BTK inhibitors were found to be beneficial in treating human systemic lupus erythematosus, rheumatoid arthritis, multiple sclerosis, Sjogren's disease, graft versus host disease, and idiopathic thrombocytopenic purpura." (PMID 38125430, 2023). "BTK is activated in monocytes and macrophages in numerous acute inflammatory conditions, including polymicrobial sepsis and cerebral ischaemia but also in chronic inflammatory conditions such as obesity‐induced diabetes, rheumatoid arthritis and lupus." (PMID 34897650, 2022). "Therefore, BTK is a promising target for novel therapeutic interventions in various immunological disorders, including rheumatoid arthritis, asthma, and systemic lupus erythematosus." (PMID 33113810, 2020). "We have recently shown that BTK protein levels are increased in circulating B cells from several autoimmune disease patients, including rheumatoid arthritis (RA), pSS, and glomerulonephritis with polyangiitis (GPA)." (PMID 35563492, 2022). "We recently identified increased levels of BTK in naïve B cells as an overarching characteristic of systemic autoimmune diseases, including rheumatoid arthritis (RA), primary Sjögren’s syndrome (pSS), and granulomatosis with polyangiitis (GPA)." (PMID 34073225, 2021). "BTK plays a critical role in the B cell receptor mediated inflammatory signaling in the rheumatoid arthritis (RA)." (PMID 28352114, 2017). "Six of these BTK inhibitors are undergoing clinical development for MS, three of which are also under investigation for chronic spontaneous urticaria (CSU), rheumatoid arthritis (RA) and systemic lupus erythematosus (SLE)." (PMID 38638671, 2024).
rheumatoid arthritis (continued). "This gave rise to the hypothesis that BTK inhibitors can be beneficial in the therapy of rheumatoid arthritis (RA), systemic lupus erythematosus (SLE), multiple sclerosis (MS), Sjögren’s syndrome (SS), allergies, and asthma." (PMID 36903645, 2023). "A study showed that spebrutinib (CC-292), a small molecular inhibitor of Bruton’s tyrosine kinase (BTK), significantly reduces the serum concentration of CXCL13 and shows a therapeutic effect on rheumatoid arthritis." (PMID 34947813, 2021). "Anti-citrullinated protein antibody (ACPA)-positive, but not ACPA-negative rheumatoid arthritis patients show elevated BTK phosphorylation relative to healthy controls, highlighting a link between overzealous BTK signaling and ACPA production." (PMID 35422819, 2022). "Mice were treated once daily with 1, 3, or 10 mg/kg evobrutinib; a dose of 3 mg/kg was previously shown to completely block disease development in mouse models of rheumatoid arthritis (RA) and systemic lupus erythematosus (SLE), and to achieve a near-complete BTK inhibition." (PMID 32761407, 2020). "Importantly, BTK appears to act as a rheostat and not as an on-off switch, with overexpression leading to autoimmunity while BTK inhibition improves outcomes of autoimmune disorders such as rheumatoid arthritis and multiple sclerosis." (PMID 35008785, 2021). "Despite enhanced BTK expression in B cells from patients with systemic lupus erythematosus (SLE) and anti-citrullinated protein antibody+ (ACPA+) but not ACPA– rheumatoid arthritis (RA), evobrutinib only showed mild effects in SLE and RA clinical trials (NCT02975336 and NCT03233230, respectively)." (PMID 35852869, 2022).